ORAI1 (ORAI calcium release-activated calcium modulator 1)
Diseases named in the same sentence as ORAI1 in open-access papers (continued):
Sharing a sentence is not in itself a finding about the gene and the disease.
autoimmune disease (8 papers, 2013 to 2025). A disorder resulting from loss of function or tissue destruction of an organ or multiple organs, arising from humoral or cellular immune responses of the individual to their own tissue constituents. "Taken together, these data support further development of antibodies for the blockade of Orai1, as well as other ion channels implicated in immune cell function, as a novel treatment strategy for autoimmune disease." (PMID 24376610, 2013). "The rs7135617 within ORAI1 was associated with an autoimmune disease, ankylosing spondylitis." (PMID 24808640, 2014). "We believe that learning the molecular background of Orai1 rearrangement to the IS can facilitate the understanding the mechanism of autoimmune diseases." (PMID 34768945, 2021). "To confirm that Orai1 is also critical for controlling the function of peripheral T cells in patients with ongoing autoimmune disease, we stimulated PBMCs isolated from RA patients with the superantigen SEB (Staphylococcus aureus enterotoxin B)." (PMID 24376610, 2013). "Human genetic studies suggest that Orai1 is a promising therapeutic target for the treatment of autoimmune diseases mediated by dysregulated T cell responses and Orai-1 is expressed in synovial fluid cells and tissue from RA patients." (PMID 24376610, 2013). "Therapeutic strategies targeting these pathways are emerging, including SOCE inhibitors for autoimmune diseases, TRP channel modulators to skew polarization toward M2 phenotypes in fibrosis, and STIM1/Orai1 antagonists in clinical trials." (PMID 40487403, 2025). "We previously showed that SOCE is essential for pathogenic Th17 cell function as mice with T cell‐specific deletion of ORAI1, STIM1 or STIM2 were protected in Th17 cell‐dependent animal models of autoimmune diseases such as EAE and colitis." (PMID 32609955, 2020). "Here, we review the role of the Ca2+-calcineurin–NFAT signaling pathway in health and diseases, focusing on the STIM and Orai1, and discuss the deregulated calcium-mediated calcineurin-NFAT pathway in autoimmune diseases." (PMID 32210952, 2020).
combined immunodeficiency (7 papers, 2020 to 2025). A broad classification of inherited disorders presenting at birth that affect both the cell-mediated and humoral aspects of the immune response. "A loss-of-function mutation in Orai1 was identified in patients with combined immunodeficiency (CID) along with severe skeletal muscle myopathy (tubular aggregate myopathy (TAM), muscular hypotonia)." (PMID 40177518, 2025). "For instance, mutations disrupting Mg2+ (MAGT1) or Ca2+ (STIM1, ORAI1) transport in lymphoid cells cause combined immunodeficiencies (CID) predominantly due to defects in functions of T cells and NK cells, rather than B cells." (PMID 37273190, 2023). "Loss‐of‐function (LOF) mutations in ORAI1 or STIM1 genes (OMIM 610277 and 605921) abolish SOCE and cause CRAC channelopathy, which is characterized by combined immunodeficiency (CID), humoral autoimmunity, and ectodermal dysplasia." (PMID 32609955, 2020). "The importance of calcium (Ca2+) as a second messenger in T cell signaling is exemplified by genetic deficiencies of STIM1 and ORAI1, which abolish store-operated Ca2+ entry (SOCE) resulting in combined immunodeficiency (CID)." (PMID 39560673, 2025).
esophageal cancer (7 papers, 2014 to 2022). A primary or metastatic malignant neoplasm involving the esophagus. "Findings of this report should greatly facilitate further investigations of the mechanisms underlying the regulation of Orai1 channels in cancer cells and thereby serve to identify targets for novel therapeutic treatments of esophageal cancer." (PMID 24797725, 2014). "Among factors that promote cell migration, the expression level of small GTPases Ras or Rac is critical in STIM1- and/or Orai1-dependent cancer types, as reported in breast and esophageal cancer cells." (PMID 36612099, 2022). "Upregulation of ORAI1 expression was observed in multiple human cancers, including non-small cell lung carcinoma, esophageal cancer and gastric cancer." (PMID 34055617, 2021). "Upregulation of Orai1 expression was observed in various human cancers, including esophageal cancer." (PMID 27259269, 2016). "The present study was undertaken to reveal the expression profile of SOCE machinery genes in tumor tissues from patients with ESCC and more importantly to explore the clinical significance of Orai1 in esophageal cancer." (PMID 24797725, 2014). "Moreover, a latest study showed that zinc may inhibit cell proliferation of esophageal cancer cells through Orai1 (a store-operated Ca2+ entry channel)-mediated intracellular Ca2+ oscillations and revealed a possible molecular basis for zinc-induced cancer prevention." (PMID 33869056, 2021).
esophageal squamous cell carcinoma (7 papers, 2014 to 2025). Esophageal squamous cell carcinoma (ESCC) is a type of esophageal carcinoma (EC) that can affect any part of the esophagus, but is usually located in the upper or middle third. "The present report is the first, to our knowledge, to reveal an oncogenic role for Orai1 in esophageal squamous cell carcinoma, a major cause of cancer death worldwide." (PMID 24797725, 2014). "Similarly, STIM1/ORAI1 overexpression in multiple myeloma or upregulation of ORAI1 in esophageal squamous cell carcinoma is associated with poorer progression-free survival." (PMID 34572262, 2021). "In esophageal squamous cell carcinoma (ESCC), Orai1-mediated hyperactive intracellular Ca2+ oscillations have been shown to promote tumorigenic behavior such as cell proliferation, migration, and invasion in both in vitro cultures and in vivo xenografted mice." (PMID 40507332, 2025). "Furthermore, revealed by time-lapse imaging, esophageal squamous cell carcinoma (ESCC) KYSE-150 cells showed hyperactive spontaneous intracellular Ca2+ oscillations, potentially due to the elevated expression of Orai1." (PMID 32599788, 2020).
glioma (7 papers, 2013 to 2025). A benign or malignant brain and spinal cord tumor that arises from glial cells (astrocytes, oligodendrocytes, ependymal cells). "High ORAI1 expression was identified as an independent adverse prognostic factor in glioma patients, significantly enriched in those with higher WHO grades (III-IV)." (PMID 41461865, 2025). "Further analysis found that the use of the inhibitor SKF96365 or RNAi downregulation of Orai1 significantly inhibited the invasion and migration of glioma cells and the epithelial-mesenchymal transition- (EMT-) like process." (PMID 31772693, 2019). "In the current study, we verified the expression of Orai1 in different grades of glioma tissues and several glioma cell lines." (PMID 25433371, 2014). "Either inhibition of SOCE by a pharmacological inhibitor or Orai1 downregulation suppressed glioma cell migration and invasion." (PMID 25433371, 2014). "The data showed that non-neoplastic brain tissues expressed low levels of Orai1, but Orai1 expression was positively correlated with the WHO grading of gliomas." (PMID 25433371, 2014). "Migration assays using Matrigel-coated Boyden chambers were performed to confirm the role of Orai1 in glioma cell invasion." (PMID 25433371, 2014). "The results showed that Orai1 promoted the invasive ability of glioma cells, suggesting that SOCE is crucial for the migration and invasion of glioma cells." (PMID 25433371, 2014). "Recent results of our research team showed that Orai1 is upregulated in glioma specimens and glioma cell lines compared with nontumor control brain tissue, and the regulatory degree is positively correlated with the grades of gliomas." (PMID 31772693, 2019). "However, the invasion of glioma cells in the Orai1 rescue group was suppressed again upon p-Pyk2 downregulation." (PMID 25433371, 2014). "Based on the results presented above, we hypothesized that modulating SOCE via targeting of Orai1 could also impact the motility of glioma cells." (PMID 25433371, 2014). "Moreover, in the RNA interference group, we established glioma cell lines stably transfected with shControl, shOrai1, or Orai1 rescue." (PMID 25433371, 2014). "On the other hand TRP and ORAI1 channels functionally interact with other family of channels: a nice example is TRPC1 which is functionally related to ClC-3 in caveolar lipid rafts of glioma cells to promote EGF-induced chemotaxis." (PMID 24204345, 2013). "The expression of Orai1, a key component of SOCE, was examined in glioma samples and glioma cell lines by immunohistochemistry and western blot analysis." (PMID 25433371, 2014). "Similarly, re-expression of Orai1 could rescue the invasive ability of glioma cells." (PMID 25433371, 2014). "However, re-expression of Orai1 could rescue glioma cell motility." (PMID 25433371, 2014). "Both Orai1 and STIM1 knockdown induced sustained proliferation inhibition in glioma C6 cells by using siRNA technology, being the effect of Orai1 silencing more prominent than that of STIM1 silencing." (PMID 23578185, 2013). "To study the role of SOCE in glioma migration and invasion, we first assessed the expression levels and subcellular localization of Orai1 in 61 glioma samples and 8 non-neoplastic brain tissues by immunohistochemistry." (PMID 25433371, 2014). "The overexpression of Orai1 in glioma tissues and cell lines leads us to believe that SOCE may be involved in the migration and invasion of glioma cells." (PMID 25433371, 2014). "Next, Orai1 protein expression was detected in non-neoplastic brain tissues, human glioma samples (WHO II and IV), and five typical glioma cell lines by western blot analysis." (PMID 25433371, 2014). "Orai1 expression was elevated in glioma tissues and several glioma cell lines compared with non-neoplastic brain tissues." (PMID 25433371, 2014). "Notably, ORAI1 expression was absent or minimal in glioma tissues but markedly elevated in patients' preoperative plasma." (PMID 41461865, 2025).
glioma (continued). "Orai1, the key component of SOCE, may become a molecular target for glioma diagnosis and treatment." (PMID 25433371, 2014). "However, as a homolog of Orai1, the role of Orai2 in gliomas has not yet been elucidated." (PMID 31772693, 2019).
ovarian carcinoma (7 papers, 2014 to 2021). A malignant neoplasm originating from the surface ovarian epithelium. "A study using paired ovarian carcinoma cell lines with different cisplatin sensitivities showed that SOCE participates in therapy resistance through elevated Orai1/STIM1 expressions and SOCE activity, accompanied by increased AKT activity." (PMID 31252656, 2019). "In conclusion, Orai1 is expressed in therapy sensitive A2780 and therapy resistant A2780cis ovary carcinoma cells." (PMID 25015419, 2014). "The difference in SOCE between therapy resistant and therapy sensitive ovary carcinoma cells is paralleled by and at least partially due to upregulation of Orai1 by Akt." (PMID 25015419, 2014). "The present observations reveal that Akt1 sensitive up-regulation of Orai1 contributes to or even accounts for cisplatin resistance of ovary carcinoma cells." (PMID 25015419, 2014). "Orai1/STIM1 have been shown to be upregulated in ovarian cancer cells resistant to chemotherapy." (PMID 32785177, 2020). "Orai1 transcript levels, Orai1 protein abundance and store operated Ca2+ entry are all higher in therapy resistant A2780cis than in therapy sensitive A2780 ovary carcinoma cells." (PMID 25015419, 2014). "The combined application of cisplatin with Akt1 inhibitors or Orai1 inhibitors may thus overcome therapy resistance of ovary carcinoma." (PMID 25015419, 2014). "We explored whether therapy resistant (A2780cis) differ from therapy sensitive (A2780) ovary carcinoma cells in Akt, Orai1, and STIM1 expression, Ca2+-signaling and cell survival following cisplatin (100μM) treatment." (PMID 25015419, 2014). "Schmidt and colleagues found that ovarian cancer cells that are resistant to CDDP express higher transcript and protein levels of Orai1, compared to CDDP-sensitive ovarian cancer cells." (PMID 34065942, 2021). "Previous studies have identified that Orai1/STIM1 expression and SOCE are increased in ovary carcinoma cells, while Akt dependent upregulation of SOCE contributes to the therapy resistance." (PMID 32079527, 2020). "More importantly, the present observations revealed that expression of both, Orai1 and STIM1, was significantly higher in therapy resistant A2780cis than in therapy sensitive A2780 ovary carcinoma cells." (PMID 25015419, 2014). "In conclusion, Orai1/STIM1 expression and function are increased in therapy resistant ovary carcinoma cells, a property at least in part due to enhanced Akt activity and contributing to therapy resistance in those cells." (PMID 25015419, 2014). "Additional experiments attempted to elucidate mechanisms accounting for the differences in Orai1 and STIM1 abundance as well as SOCE between therapy resistant A2780cis and therapy sensitive A2780 ovary carcinoma cells." (PMID 25015419, 2014). "The present study disclosed the expression of Orai1 and STIM1 in both, therapy sensitive A2780 and therapy resistant A2780cis ovary carcinoma cells." (PMID 25015419, 2014). "Furthermore, the expression of Orai1/STIM1, as well as SOCE activity, is enhanced in cisplatin-resistant ovarian carcinoma cells when compared with the therapy-sensitive parental cells." (PMID 31252656, 2019). "The present study explored whether Orai1 and STIM1 are expressed in ovary carcinoma cells and whether their expression and function differs between therapy resistant and therapy sensitive ovary carcinoma cells." (PMID 25015419, 2014). "RT-PCR was employed to explore whether ovary carcinoma cells transcribe Orai1 and/or STIM1 and whether the transcript levels are different between therapy sensitive A2780 and therapy resistant A2780cis ovary carcinoma cells." (PMID 25015419, 2014). "Finally, in ovarian carcinoma, STIM and ORAI1 were found to be more strongly expressed in cisplatin-resistant cells (A2780cis) than in their sensitive counterpart (A2780), and the combination of cisplatin with 2-APB, a SOC inhibitor, restored A2780cis sensitivity." (PMID 30338034, 2018).
ovarian carcinoma (continued). "The Orai1 inhibitor 2-APB (50 μM) decreased the peak Ca2+ increase from 0.19 ± 0.02 arbitrary units (n = 6) to 0.07 ± 0.01 arbitrary units (n = 5) in A2780 ovary carcinoma cells and from 0.49 ± 0.03 arbitrary units (n = 6) to 0.04 ± 0.01 arbitrary units (n = 5) A2780cis ovary carcinoma cells." (PMID 25015419, 2014).
pancreatic cancer (7 papers, 2020 to 2024). "Whereas there is a very limited number of studies focusing on the importance of Orai1-CRAC channels in pancreatic cancer, we have previously demonstrated the functional expression of Orai1 in several pancreatic ductal adenocarcinoma cell lines." (PMID 34063470, 2021). "The pivotal proapoptotic role of STIM1/ORAI1 was first noted in pancreatic cancer where downregulation of ORAI1 or ectopic expression of its dominant-negative mutant reduced the susceptibility of tumor cells to apoptotic stimuli." (PMID 34572262, 2021). "While it is well known that PSC activation mediates pancreatic tumor’s desmoplastic reaction, this study is one of the first pieces of evidence showing the functional expression and role of the Orai1-Ca2+ channel in human PSCs’ activation processes." (PMID 34063470, 2021). "Therefore, blocking STIM1 and ORAI1 has been shown to enhance apoptosis in pancreatic cancer cells induced by chemotherapeutic agents like 5-fluorouracil (5-FU) and gemcitabine." (PMID 39682132, 2024). "Apoptosis of pancreatic cancer cells induced by chemotherapeutic agents such as 5-fluorouracil (5-FU) and gemcitabine can be enhanced by blocking STIM1 and Orai1." (PMID 37932320, 2023). "For example, reduced Orai1 and STIM1 activity increases apoptosis of pancreatic cancer cells, and the in vivo silencing of Orai1 in mice protects macrophages from apoptosis." (PMID 34944425, 2021). "For instance, in pancreatic cancer, STIM1 and Orai1 exert an inhibitory effect on apoptosis." (PMID 37932320, 2023). "Furthermore, it has recently been established that Orai1 inhibition, using the RP4010 CRAC channel inhibitor, decreased pancreatic cancer cell proliferation through the down-regulation of the AKT/mTOR signaling pathway." (PMID 34063470, 2021). "The IC50 of RP4010 for ORAI1 knocked down cells (siORAI1) increased by almost 76% as compared with the control cells (32.89 μM vs. 18.7 μM), indicating that the effect of RP4010 on the proliferation of pancreatic cancer cells mainly stems from its ability to inhibit CRAC channel." (PMID 32235707, 2020).
ankylosing spondylitis (6 papers, 2011 to 2020). An autoimmune chronic inflammatory disorder characterized by inflammation in the vertebral joints of the spine and sacroiliac joints. "Genetic polymorphisms of ORAI1 were reported to be associated with a risk of HLA-B27-positive ankylosing spondylitis." (PMID 24808640, 2014). "Previous studies have revealed the significant association between genetic polymorphisms of ORAI1 and inflammatory diseases such as ankylosing spondylitis and calcium nephrolithiasis." (PMID 22253717, 2012). "In addition to these results, other studies also reported that polymorphisms of ORAI1 are involved in other diseases such as ankylosing spondylitis and Kawasaki disease." (PMID 33182378, 2020). "Furthermore, the ORAI1 haplotypes (rs12313273 and rs7135617) are associated with the risk of HLA-B27-positive ankylosing spondylitis." (PMID 24745010, 2014). "Haplotype frequency of the ORAI1 gene in HLA-B27(+) or HLA-B27(-) patients with ankylosing spondylitis and controls." (PMID 21674042, 2011).